XRCC1 (X-ray repair cross complementing 1)
Diseases named in the same sentence as XRCC1 in open-access papers (continued):
Sharing a sentence is not in itself a finding about the gene and the disease.
ovarian carcinoma (continued). "In co-immunoprecipitation experiments, in ovarian cancer cell lines, we also observed that Mre11 physically interacted with Nbs1, Rad50, XRCC1 and LIG3 consistently in PEO1 cells." (PMID 35853939, 2022). "Patients with positive XRCC1 expression are more likely to have adverse clinicopathological and survival outcomes, which is considered a new predictive marker for ovarian cancer." (PMID 35379200, 2022). "XRCC1 overexpression has been shown to increase resistance to DNA-damaging chemotherapeutics in gastric and ovarian cancers, while low XRCC1 is correlated with hypersensitivity to DNA-damaging agents." (PMID 35457130, 2022). "FEN1 overexpression is associated with an increased aggressive phenotype and poor prognosis of cancer after cisplatin chemotherapy, while inhibition of Pol β or XRCC1 can enhance the sensitivity of ovarian cancer to cisplatin treatment." (PMID 35883563, 2022). "Together, these results indicate the potential of XRCC1 to be used as a target for drug-resistant ovarian cancer." (PMID 36551731, 2022). "The results illustrated that decreasing the expression of XRCC1 using inhibitors of heat shock protein 90 reversed cisplatin resistance in SKOV3/DPP ovarian cancer cells." (PMID 36551731, 2022). "In this two-center case-control study, 19 potentially functional SNPs in six BER-related genes (hOGG1, APE1, PARP1, FEN1, LIG3 and XRCC1) was genotyped in 196 ovarian cancer cases and 272 cancer-free controls." (PMID 33391423, 2021). "We have previously shown that FEN1 17, RPA1 (manuscript under preparation) and XRCC1 18 are key predictor of platinum resistance in ovarian cancers." (PMID 34373746, 2021). "In ovarian cancers, overexpression of the BER pathway proteins FEN1 and XRCC1 are reportedly linked to high clinical stage and poor survival." (PMID 34712221, 2021). "Some important associations of ERCC1, XRCC1 and GSTP1 polymorphisms of clinical outcomes and adverse events in Thai epithelial ovarian cancer patients were noticed." (PMID 32711417, 2020). "As in previous reported, ERCC1, XRCC1 and GSTP1 polymorphisms had impacts on treatment responses of platinum based chemotherapy among epithelial ovarian cancer patents." (PMID 32711417, 2020). "In this study, we observed that XRCC1 expression was up-regulated in GBC compared with non-tumor tissues, which was consistent with previous studies where XRCC1 was overexpression in ovarian cancer and head and neck squamous cell cancer." (PMID 32426369, 2020). "For example, in gastric and ovarian cancer, patients with low XRCC1 expression exhibited favorable response to platinum-based chemotherapy." (PMID 32426369, 2020). "We conducted the study to investigate the association between polymorphisms of ERCC1, XRCC1 and GSTP1, which responsible for platinum’s metabolisms in Thai epithelial ovarian cancer patients." (PMID 32711417, 2020). "Significant expression changes were also confirmed by RT-qPCR for some genes involved in homologous (HR) and non-homologous end joining (NHEJ) DNA damage-repair mechanisms in ovarian cancer, such as XRCC1 in EOC-CC1, and XRCC4, RAD51 and BRCA2 in OSPC2." (PMID 28482906, 2017). "We have recently shown that XRCC1 is key predictive biomarker of platinum resistance in ovarian cancers." (PMID 26674120, 2014). "Previously we have demonstrated that XRCC1, a key player in DNA base excision repair, is an important prognostic and predictive biomarker in ovarian cancer." (PMID 26674120, 2014). "ATM +/XRCC1 +, DNA-PKcs +/XRCC1 + and ATR +/XRCC1 + tumours have significantly worse ovarian cancer specific survival and progression free survival compared to tumours that are ATM-/XRCC1-, DNA-PKcs-/XRCC1- and ATR-/XRCC1- respectively (ps ≤ 0.001)." (PMID 26674120, 2014). "In the current study, we investigated synthetic lethality in XRCC1 deficient and XRCC1 proficient Chinese Hamster ovary (CHO) and human ovarian cancer cells using ATR inhibitors (NU6027)." (PMID 23451157, 2013).
ovarian carcinoma (continued). "XRCC1 plays a crucial role in coordinating and stabilizing interactions between repair proteins, while the rs25487 polymorphism weakens these interactions, leading to decreased DNA repair efficiency in the BER pathway, particularly in ovarian cancer." (PMID 40647471, 2025). "Then, we focused on genes traditionally associated with breast/ovarian cancer or other malignancies, and identified 23 missenses, 2 splicing, and 2 UTR variants mainly affecting genes involved in DNA repair, such as RAD51, RAD54B, PMS1, FANCD2, XRCC1, and BLM." (PMID 35893033, 2022). "This therapy was selectively toxic to Pol β-deficient ovarian cancer cells, but not to XRCC1-deficient ovarian cancer cells." (PMID 35883563, 2022). "Along with SNPs in two other NER proteins, XRCC1 and XRCC2, the XPC Ala499Val polymorphism was found to correlate to a decreased odds of ovarian cancer (OR 0.35) while the XPC Lys939Gln polymorphism was associated with an increased risk of ovarian cancer (OR 1.72) in a dominant genetic model." (PMID 35530314, 2022). "Although in XRCC1 deficient ovarian cancer cell, FEN1i was not selectively toxic, in polβ_KO ovarian cancer cells FEN1i induced synthetic lethality." (PMID 33919707, 2021). "This indicated that XRCC1 gene expression in peripheral blood may affect the sensitivity of cisplatin chemotherapy for ovarian cancer." (PMID 34918657, 2021). "FEN1i treatment was selectively toxic to POLβ deficient but not XRCC1 deficient ovarian cancer cells." (PMID 33919707, 2021). "Since we had previously shown that POLβ or XRCC1 deficiency is a predictor of platinum sensitivity in ovarian cancers, we investigated whether a synthetic lethality relationship exists between FEN1 and either POLβ or XRCC1." (PMID 33919707, 2021). "Therefore, DNA repair proteins, XRCC1 and PARP1, have been associated with significantly aggressive clinical outcome of ovarian cancer patients and decreased cisplatin sensitivity in OC cells." (PMID 33076245, 2020). "The association between genetic polymorphisms of ERCC1, XRCC1 and GSTP1 with progression free survival (PFS) and overall survival (OS) in patients with epithelial ovarian cancer in varies ethnicities such as American, European or Asian were reported in several studies." (PMID 32711417, 2020). "We did not observe a significant association between XRCC1 rs25489 and risk of ovarian cancer, even though estrogens and their metabolites damage DNA by forming bulky DNA adducts, which are normally repaired by the BER pathway." (PMID 28415705, 2017). "Our data therefore suggests that XRCC1 is a promising biomarker in ovarian cancer." (PMID 23451157, 2013). "We generated XRCC1 knockdown human ovarian cancer cell lines using three siRNA constructs." (PMID 23451157, 2013). "Therefore, research to investigate the association of ERCC1, XRCC1 and GSTP1 polymorphisms with clinical treatment responses and adverse events from platinum-based chemotherapy especially in Thai patients with advanced epithelial ovarian cancer was needed." (PMID 32711417, 2020). "We evaluated the clinical significance of XRCC1 and LIG1 protein co-expression in human ovarian cancers." (PMID 34373746, 2021). "We have previously shown that XRCC1, a key scaffolding protein and a partner for LIG3 or LIG1 is a key predictor of platinum sensitivity in ovarian cancer." (PMID 34373746, 2021). "Here, we have conducted an exploratory stratification analysis based on XRCC1 status and ATM/DNA-PKcs/ATR expression in ovarian cancer." (PMID 26674120, 2014). "In a clinical study, XRCC1-positive epithelial ovarian cancer tumors were significantly more likely to be platinum-resistant compared to XRCC1-negative tumors." (PMID 36551731, 2022). "Taken together, our data suggests that XRCC1 based personalization using ATM, DNA-PKcs or ATR inhibitors may be feasible and this approach clearly warrants further investigation in vivo in sporadic epithelial ovarian cancers." (PMID 26674120, 2014).
cervical carcinoma (29 papers, 2009 to 2026). A carcinoma arising from either the exocervical squamous epithelium or the endocervical glandular epithelium. "At present, most studies have shown that the XRCC1 gene polymorphism is related to the risk of cervical cancer, and few studies have examined its expression in cervical cancer." (PMID 35379200, 2022). "They showed that the TGFB1 T10C and XRCC1 G399A polymorphisms were associated with cervical cancer risk." (PMID 34837895, 2021). "Our results suggested that, XRCC1 gene is an important candidate gene for susceptibility to cervical cancer." (PMID 32711433, 2020). "Although the sample size was small, the present study indicate a statistical association between cervical cancer and XRCC1 SNPs." (PMID 32711433, 2020). "The “A” allele of rs25487 was considered as a leading allele for an increased risk of cervical cancer, as there is a significant association of XRCC1 gene polymorphism with cervical cancer." (PMID 30616520, 2019). "So a meta-analysis of ten available studies involving 2092 cervical cancer cases and 2803 controls was performed, expecting to derive a more precise estimation of the association between the XRCC1 polymorphism and cervical cancer susceptibility." (PMID 27903984, 2017). "In terms of XRCC1 Arg399Gln polymorphism, ten studies involving 1635 cancer patients and 2361 controls presented available data about this locus and cervical cancer risk." (PMID 27903984, 2017). "Results also showed that the XRCC1 rs3213245 C genotype decreases the risk of cervical cancer by upregulating the tumoral XRCC1 transcription in cervical cancer patients." (PMID 29156789, 2017). "With regard to XRCC1 Arg280His polymorphism, four articles including 2015 objects (784 cases and 1231 controls) offered data about the association between it and cervical cancer risk." (PMID 27903984, 2017). "Results indicated that the XRCC1 rs3213245 (-77TC) TT genotype was associated with an increased risk of cervical cancer." (PMID 29156789, 2017). "Certainly, to further evaluate the association between XRCC1 polymorphisms and cervical cancer susceptibility, a well-designed large-scale multicenter study is warranted to confirm the finding." (PMID 27903984, 2017). "XRCC1 polymorphisms were thought to be closely related to many cancers, such as cervical cancer, non-small cell lung cancer and childhood acute lymphoblastic leukemia." (PMID 29155820, 2017). "Pooled odds ratios (OR) with 95% confidence intervals (95% CI) were employed to evaluate the strength of associations between the XRCC1 polymorphisms and cervical cancer risk." (PMID 27903984, 2017). "In summary, the findings indicated that the functional XRCC1 SNP rs3213245 was associated with the risk of cervical cancer based on the Sp1/Krox-20 switch." (PMID 29156789, 2017). "A great many epidemiologic studies have been conducted to evaluate the role of the XRCC1 polymorphisms (Arg194Trp, Arg280His and Arg399Gln) on cervical cancer risk." (PMID 27903984, 2017). "Certainly, there have emerged several other meta-analysises concerning the link between XRCC1 polymorphisms and cervical cancer risk." (PMID 27903984, 2017). "For XRCC1 Arg194Trp polymorphism, there were seven studies, involving 1315 cases and 1633 controls, evaluating the connection between it and cervical cancer susceptibility." (PMID 27903984, 2017).
cervical carcinoma (continued). "In conclusion, we have shown that the transcription factor Krox-20 was recruited to the XRCC1 rs3213245 mutation region and regulated the transcription of the XRCC1 gene by interacting with Sp1, ultimately mediated cervical cancer development." (PMID 29156789, 2017). "X-ray repair cross-complementing protein 1 (XRCC1) polymorphisms were also associated with response to platinum-based NAC in cervical cancer patients." (PMID 27487151, 2016). "The XRCC1 194Arg allele variant shows association with susceptibility to cervical cancer in homozygous (Arg194Arg) and heterozygous (Arg194Trp) states." (PMID 23675381, 2013). "Our research revealed the strong protective effect of XRCC1 194Trp allele in cervical cancer patients." (PMID 23675381, 2013). "Only XRCC1 SNP was significantly associated with cervical cancer (P=0.02, OD=1.69; 95% CI= 1.06–2.66)." (PMID 23642098, 2013). "Polymorphism of 399 codon of XRCC1 gene also shows association with susceptibility to cervical cancer." (PMID 23675381, 2013). "We found out that XRCC1 Arg194Trp polymorphism had been associated with esophageal and cervical cancer in Kazakhstan population, but in different manner." (PMID 23675381, 2013). "XRCC1 Trp194Trp genotype was associated with susceptibility to esophageal cancer, and XRCC1 Arg194Arg genotype – with cervical cancer." (PMID 23675381, 2013). "Our findings suggest that the genotype with at least one Gln allele probably increases the expression of XRCC1 protein, and consequently, results in poor response to platinum-based chemotherapy in patients with locally advanced cervical carcinoma." (PMID 19563645, 2009). "In the DNA damage repair gene XRCC1, the allelic frequency of the SNP rs25487 is reduced in the Chilean population compared to the Admixed American population, and this SNP has previously been associated with an increased risk of cervical cancer." (PMID 38675222, 2024). "The variant of XRCC1 codon 399 was also associated with 3.44 fold higher risk in cervical cancer." (PMID 32711433, 2020). "We did not found any evidence for a combined effect of the 194Trp and 399Gln alleles of XRCC1 and CC development but, 280His and 399Gln genotype of XRCC1 may be collectively related to cervical cancer risk." (PMID 32711433, 2020). "Our findings confirm the association of XRCC1 rs25487 with an elevated risk for cervical cancer." (PMID 30616520, 2019). "Likewise, some limitations of this meta-analysis should be mentioned even though considerable effort and resources have been put into testing the possible association between the XRCC1 polymorphism and cervical cancer risk." (PMID 27903984, 2017). "Because a single study may have been underpowered to detect the effect of XRCC1 polymorphisms on cervical cancer risk, yet a quantitative synthesis of accumulative data from all available studies may provide convincing evidence." (PMID 27903984, 2017). "Moreover, ChIP/Re-ChIP assays revealed that transcription factor Krox-20 was recruited to the XRCC1 rs3213245 mutation region and regulated the transcription of the XRCC1 gene by interacting with Sp1, ultimately mediated cervical cancer development." (PMID 29156789, 2017). "There are data confirming the participation of XRCC1-genes polymorphism to cervical cancer." (PMID 23675381, 2013). "Stratified analyses of the XRCC1 polymorphism Arg399Gln on cervical cancer (CC) risk." (PMID 22984511, 2012). "In comparison to these studies, our findings suggest that CpG-ODNs may alleviate renal injury caused by cervical cancer radiotherapy (RKI) by inhibiting the activation of the PARP1/XRCC1 signaling axis, thus suppressing DNA damage and oxidative stress responses in renal tubular epithelial cells." (PMID 37773127, 2023).
cervical carcinoma (continued). "However, they showed that he XRCC1+399A/G is linked with cervical cancer in the Indian population." (PMID 34837895, 2021). "Because XRCC1 is one of the most important DNA repair genes, the main aim of the present study was to determine whether the XRCC1 genetic polymorphisms could predict clinical response of patients with locally advanced cervical carcinoma to platinum-based NAC." (PMID 19563645, 2009). "In radiation-induced kidney injury associated with cervical cancer, PARP1 interacts with X-ray repair cross-complementing 1 (XRCC1) to form a complex, which subsequently induces DNA damage and oxidative stress response in renal tubular cells." (PMID 40911105, 2025). "Association of genotypes of CYP1A1 T>C rs4646903, CYP1A1 A>G rs1048943, CYP2E1 T>A rs6413432, RAD51 G>C rs1801320, XRCC1 G>A, rs25487 XRCC2 G>A rs3218536 and XRCC3 C>T rs861539 polymorphisms with clinical response of cervical cancer cases (n = 227)." (PMID 35996502, 2022). "Association of genotypes of CYP1A1 T>C rs4646903, CYP1A1 A>G rs1048943, CYP2E1 T>A rs6413432, RAD51 G>C rs1801320, XRCC1 G>A rs25487, XRCC2 G>A rs3218536 and XRCC3 C>T rs861539 polymorphisms and survival after treatment (CRT) for cervical cancer." (PMID 35996502, 2022). "Association of genotypes of CYP1A1 T>C rs4646903, CYP1A1 A>G rs1048943, CYP2E1 T>A rs6413432, RAD51 G>C rs1801320, XRCC1 G>A, rs25487 XRCC2 G>A rs3218536 and XRCC3 C>T rs861539 polymorphisms with vital status and recurrence of cervical cancer cases (n = 227)." (PMID 35996502, 2022). "We identified and studied the association of Single Nucleotide polymorphisms in the DNA repair genes of XRCC1 (Arg194Trp, Arg399G,) and APE-1Asp/148Glu to the susceptibility of cervical cancer (CC) in North Indian population." (PMID 32711433, 2020). "But fewer published information is available regarding the association between polymorphism of XRCC1, and APE148 gene and susceptibility to cervical carcinoma." (PMID 32711433, 2020). "For XRCC1 A399G, the previous report in Thai cervical cancer patients was 22% which quite similar to 28.9% in our findings." (PMID 32711417, 2020). "The IHC assay showed that the XRCC1 protein expression levels were upregulated in cervical cancer patients with the XRCC1 rs3213245 CC genotype compared with the CT or TT genotypes according to the staining scores." (PMID 29156789, 2017). "The present meta-analysis was intended to explore the relationship between the X-ray repair cross complementing 1 (XRCC1) polymorphisms (Arg194Trp, Arg280His and Arg399Gln) and cervical cancer risk." (PMID 27903984, 2017).